CCDC121 (coiled-coil domain containing 121)
Synonyms: FLJ43364; FLJ13646
Tractability: PROTAC: ubiquitination databases record sites on it.
Gene: Protein-coding gene on chromosome 2 (27,625,638 to 27,629,012, reverse strand). Ensembl gene ENSG00000176714.
Subcellular location (Human Protein Atlas): Actin filaments; Cytosol
Gene Ontology:
Molecular function: protein binding
Genetic constraint (gnomAD): Loss-of-function variants: 0 observed, 0.42 expected, observed/expected ratio (o/e) 0, 90% interval 0 to 1.85. That is too few expected variants to judge how well the gene tolerates losing a copy. Missense variants: 238 observed, 312.26 expected, observed/expected ratio (o/e) 0.76, 90% interval 0.69 to 0.85. Synonymous variants: 108 observed, 122.8 expected, observed/expected ratio (o/e) 0.88, 90% interval 0.75 to 1.03.
Homologues: Orthologues: chimpanzee CCDC121 (99% identical), macaque CCDC121 (94% identical), dog CCDC121 (63% identical).
Diseases named in the same sentence as CCDC121 in open-access papers:
CCDC121 is named in the same sentence as 6 diseases in open-access papers, as found by Europe PMC text mining. Sharing a sentence is not in itself a finding about the gene and the disease. The quoted sentences say what the papers report.
neuropathy (1 paper, 2024). A disorder affecting the nervous system that manifests with pain, tingling, numbness, and/or muscle weakness. "The second gene CCDC88C has no documented association with neuropathy, but CCDC121 in the same family has been associated with cytotoxicity and TIPN32." (PMID 38755266, 2024).
CCDC121 also shares sentences with these, for which no sentence is quoted: cancer (2 papers); chronic gastritis (1); gastric cancer (1); metastatic cancer (1); tumour diseases (1).